IL21 (interleukin 21)
Diseases named in the same sentence as IL21 in open-access papers (continued):
Sharing a sentence is not in itself a finding about the gene and the disease.
tumor (continued). "While recombinant IL-21 has been investigated in cancer patients to enhance anti-tumor immunity, in transplantation, IL-21 is more likely to contribute to allograft rejection." (PMID 40376002, 2025). "Nanocarriers can deliver cytokines like IL-15 and IL-21, checkpoint inhibitors, or gene-editing tools directly to NK cells or the tumor microenvironment." (PMID 41375063, 2025). "Despite having higher death rates than the IL-15 NK cells, the higher proliferation pc, cytotoxicity pkill, and SKC S0 of the IL-21 NK cells contributed to more rapid tumor control." (PMID 40027823, 2025). "Oncolytic vaccinia viruses express IL-2, IL-10, IL-12, IL-15, IL-21, IL-23, IL-24, and IL-36γ remodel the tumor microenvironment,enhance immune cell infiltration, suppress immunosuppressive elements and promot systemic antitumor immunity." (PMID 40469178, 2025). "In the pathogenesis of this cancer, significant importance is attributed to interactions between tumour cells and the tumour microenvironment, in which soluble immune system mediators—cytokines—play a key role, including IL-21 and IL-22." (PMID 40729006, 2025). "The aim of this study was to determine the concentrations of IL-21 and IL-22 in a group of patients with invasive cancer, depending on the biological type of the tumour and its malignancy grade." (PMID 40729006, 2025). "A new generation VV armed with interleukin-21 (IL-21) synergized with anti-PD1 therapy promoted durable immune memory to achieve long-term tumor control in murine models." (PMID 40805247, 2025). "It is well-known that CD8 T cells play a crucial role in anti-tumor immunity, and IL-21 can effectively enhance this effect." (PMID 40376002, 2025). "IL-21 was also reported to be capable of re-activating the exhausted cytotoxicity of CD8+ T cells that reside in the tumor microenvironment." (PMID 40722671, 2025). "Here, we report the design of novel trifunctional tumor-directed antibody-cytokine fusion protein formats combining IL-15 with IL-21 or IL-7." (PMID 40370435, 2025). "A recent study revealed that interactions between intratumoral CD4+ T cells and B cells induce the generation of tumor-specific follicular helper T (Tfh) cells; these Tfh cells then secrete IL-21 to enhance the anti-tumor effects of CD8+ T cells." (PMID 41285707, 2025). "At the same time, CD4+ T cells can regulate the tumor microenvironment by secreting cytokines like IL-12 and IL-21, further promoting CD8+ T cell infiltration and function." (PMID 40936903, 2025). "In this study, we demonstrate that arming CAR-NK cells with IL-21 enhances their effector function and provides long-lasting anti-tumor activity through metabolic reprogramming, compared to CAR-NK cells modified to express with IL-15." (PMID 40176196, 2025). "The anti-tumor effect of Tfh-dependent TLSs is mediated via interleukin-21 (IL-21)-IL-21 receptor signaling; inhibition of TLSs formation through depletion of Tfh cells or B cells promotes tumor growth." (PMID 41285707, 2025). "Here, we investigated the molecular design of tumor-directed trifunctional antibody-cytokine fusion proteins for a combinatorial approach of IL-15 with either IL-7 or IL-21." (PMID 40370435, 2025). "In this study, we reported that engineering CAR-NK cells to express IL-21 resulted in enhanced anti-tumor activity compared to CAR-NK cells expressing IL-15." (PMID 40176196, 2025). "We demonstrated that VS-induced SNHL was linked to increased secretion of TNF-α, IL-2R, CD163, eotaxin, and HGF, while larger tumor size was associated with higher levels of TNF-α, TNF-R2, IL-1α, IFN-α, MIP-1β, and IL-21 secretion." (PMID 39923035, 2025). "Compared to NKG2D CAR-NK-92 cells, mice treated with these cells showed significantly reduced tumor volumes and higher serum levels of IL-21 and IFN-γ." (PMID 41301424, 2025). "Integrating cytokines like interleukin-21 (IL-21) with TCR-T cell therapy can significantly enhance anti-tumor responses." (PMID 40308592, 2025).
tumor (continued). "Cairo and colleagues developed a CAR NK cell targeting ROR1 and demonstrated the anti-tumor efficacy of the combination of an oncolytic virus engineered to secrete IL-21 (C021) with anti-ROR1-CAR-NK cells against NB." (PMID 39895691, 2025). "IL-21 induced GrBhi Breg is enriched in tumour tissue and promotes GrB-dependent degradation of TCR, inhibiting T cell proliferation." (PMID 39346706, 2024). "We also found that a cytokine cocktail (IL-2, IL-9 and IL-21) can effectively amplify the anti-tumour effect." (PMID 39215816, 2024). "Tfh cells promote B cell activation and antibody conversion into anti-tumor IgG1 and IgG3 through IL-21, thereby promoting B cell-mediated humoral anti-tumor immunity." (PMID 39575712, 2024). "IL-21 combined with PD-1 or CTLA-4 monoclonal antibodies can slow down tumor growth and increase CD8 + T-cell proliferation and infiltration." (PMID 38833177, 2024). "Analysis of multiple tumour types revealed tumour infiltrating GrB+ Bregs adjacent to IL-21-secreting Treg, suggesting a mechanism within the tumour microenvironment." (PMID 39346706, 2024). "generated an Erbitux-based IL-21 fusion protein (Erb-IL-21) to target tumor cells expressing chimeric EGFR (cEGFR)." (PMID 38638431, 2024). "Ultimately, the combination of MWA with IL-21 and anti-PD-1 mAbs further amplified the anti-tumor effect." (PMID 38833177, 2024). "Our findings demonstrate that the combination of MWA with IL-21 and anti-PD-1 mAbs is highly effective in suppressing tumor growth." (PMID 38833177, 2024). "AFP-TCR-T expressing a novel engineered IL-21R with constitutive IL-21 signal showed increased proliferation and tumor-infiltrating capacity, resistance to antigen-induced cell death, and superior antitumor function compared with conventional AFP-TCR-T." (PMID 38643203, 2024). "Given the expression of IL-21 in NKG2D-IL-21 CAR-NK-92 cells and its established role in enhancing cytotoxic activity, our investigation focused on evaluating the in vitro anti-tumor effects of NKG2D-IL-21 CAR-NK-92 cells." (PMID 38263004, 2024). "Th17 cells secrete cytokines such as interleukin-17 (IL-17) and interleukin-21 (IL-21), which positively regulate the functions of Th1 and NK cells, thereby mediating anti-tumor immune responses." (PMID 39596288, 2024). "Elevated IL-21-induced GrB+ Bregs have been found in the tumour microenvironment (TME) of breast, ovarian, cervical, colorectal, and prostate carcinomas." (PMID 39346706, 2024). "Combinations of IL-21 with α-galactosylceramide conferred higher antitumor activity in experimental tumor metastases by activation of NK cells induced by NKT cells." (PMID 38638431, 2024). "IL-21 plays a key pro-inflammatory role in stimulating differentiation of B cells, promoting anti-viral and anti-tumor effects of CD8+ T cells, and inducing Th17 cells which secrete IL-17, recruit neutrophils, and link innate and adaptive immunity." (PMID 39250522, 2024). "Overall, combining IL-21 with other immuno-stimulants, monoclonal antibodies that recognize specific tumor antigens or chemotherapy for cancer treatment showed better performances than monotherapy." (PMID 38638431, 2024). "These circulating CD4(+) T cells contribute to the activation of peripheral blood CD8(+) T cells within the tumor microenvironment through the production of IL-21, thereby enhancing the cytotoxic function of infiltrating CD8(+) T cells." (PMID 38395827, 2024). "IL-21 was fused with an anti-PD-1 (PD-1Ab21) to target tumor-reactive T cells and exhibited potent anti-tumor effects." (PMID 38833177, 2024). "The phenotypic change of IL-2 or IL-21-supplemented TCR-T during repetitive tumor antigen stimulation was also monitored." (PMID 38643203, 2024). "Th17 cells express the cytokines IL-17, IL-21, IL-22 and other cytokines such as IFNγ and TNFα in human tumor tissues." (PMID 38833034, 2024).
tumor (continued). "Erb-IL-21, which is an Erbitux-based IL-21 tumor-targeting fusion protein and features asymmetric structure, demonstrated prolonged half-life and improved antitumor efficacy." (PMID 39664443, 2024). "Our study shows that IL-21 can be combined with checkpoint inhibitors to improve the anti-tumor effect of MWA." (PMID 38833177, 2024). "In pancreatic cancer, neoadjuvant chemotherapy reversed the PD‐L1/PD‐1‐mediated inhibition of Tfh cells, enabling CXCL13‐mediated recruitment of B cells and IL‐21‐driven differentiation of PCs, ultimately enhancing anti‐tumour immunity." (PMID 38997802, 2024). "Our results saw an enrichment of IL-12, IL-21, Th17 cell lineage commitment, and NK cell activation pathways: Natural killer cells recognize and cytolyze tumor cells during normal immunosurveillance or as part of the immune response to tumors." (PMID 38750495, 2024). "Various genes with tumor suppressor functions, such as chemokine ligand-11, IL-21, IL-27, CD40L, chemokine ligand-9, IL-9, and IL-15, were upregulated in DBMSCs after treatment with MDA231 cells in an IC setting." (PMID 39768220, 2024). "adopted an alternative strategy and generated a PD-1Ab21 construct by fusing an anti-PD-1 antibody with IL-21 to increase the generation of memory stem T cells and induce the expansion of tumor-specific CD8+ T cells with a memory phenotype." (PMID 38638431, 2024). "Interleukin-12 (IL-12) performs a similar role to IL-21 in the immune system and is described as potentially one of the most powerful anti-tumor, pro-immune cytokines, with increased potency compared to IL-21." (PMID 39840061, 2024). "The anti-tumor effects of IL-21 have been extensively studied in various preclinical mouse tumor models, combining IL-21 and immune checkpoint inhibitors exerts more effective anti-tumor effects." (PMID 38833177, 2024). "In tumor cells, IL-21 enhances the immune response by increasing the cytotoxic activity of natural killer cells, B cells, and CD8+ T cells, leading to tumor cell apoptosis." (PMID 39192980, 2024). "IL-21 plays a pivotal role in anti-tumor immune responses due to its capacity to augment the cytotoxic activity of both CD8 + T cells and NK cells." (PMID 38833177, 2024). "It has been reported that IL-21 produced by CD4+ T helper cells enhances the effector functions of CD8+ tumor-infiltrating lymphocytes (TILs) through IL-21/IL-21R signaling." (PMID 39338178, 2024). "In this study, we have found that combining MWA with IL-21-αHSA can enhance the anti-tumor effect and prolong the survival of tumor-bearing mice." (PMID 38833177, 2024). "Our results show that MWA combined with IL-21 inhibits tumor growth and prolongs the survival of mice." (PMID 38833177, 2024). "VVL-expressing interleukin-21 (IL-21) exhibits good safety and anti-tumor efficacy against various types of tumors." (PMID 39830516, 2024). "Our results found that the use of FTY720 before ablation abolished the synergistic anti-tumor effect of MWA combined with IL-21, and immune cells in peripheral blood and TME significantly decreased." (PMID 38833177, 2024). "The ability of IL-21 to regulate diverse immune cells together with its angiostatic properties confer this cytokine a potent ability to drive tumor cells clearance." (PMID 38638431, 2024). "We also found that the combined anti-tumor effect of IL-21 and MWA is dependent on circulation of immune cells." (PMID 38833177, 2024). "IL-21 was shown to impair the development and homeostasis of regulatory T-cells (Treg), which are abundant in tumor tissues, both in human and mice." (PMID 38638431, 2024). "Although therapies based on TA or IL-21 have exhibited promising advancements, they still encounter obstacles in achieving substantial tumor eradication." (PMID 38833177, 2024). "Given the increase in pro-inflammatory CD4(+) T cells after oHSV treatment, we next analyzed IFN-γ, TNF-α, IL-4, IL-17A, and IL-21 intracellular expression within the CD4(+) tumor infiltrates." (PMID 38895115, 2024).
tumor (continued). "Analysis of genes related to TIME revealed no significant expression changes, except for the relative overexpression of LAG3 in tumor‐infiltrating immune cells and a relative decrease in IL21 expression." (PMID 39565059, 2024). "Upon no activation differences were observed, we expanded CAR T cells with IL15 and IL21 because recent studies show that combined expression of IL-15 and IL-21 result in a less differentiated profile and longer survival in repeated exposures to tumor cells." (PMID 39478867, 2024). "IL-21 plays an important role in the anti-tumor immune response and has been tested as an anti-tumor drug in various preclinical and clinical models." (PMID 38833177, 2024). "Adoptive transfer of NK cells expanded with irradiated membrane-bound IL-21/4-1BBL-expressing K562 cells into tumor-bearing mice induced the tumor regression and improved animals survival, indicating a potent therapeutic effect of these NK cells." (PMID 38638431, 2024). "In this study, we biologically engineered NK cells to express NKG2D and IL-21 and explored the anti-tumor activities of these CAR-NK cells." (PMID 38263004, 2024). "Biodistribution experiments showed that this construct did not preferentially accumulate in the tumor site due to the peripheral binding of IL-21, highlighing the need to engineer IL-21 to improve its binding and activity at the tumor site." (PMID 39204319, 2024). "The adoptive transfer of IL-21 boosted NK cells expansion after radiation therapy induced tumor regression in an RMS xenograft model." (PMID 38638431, 2024). "IL-21 arming potentiated the anti-tumor activity of oncolytic VACVs by increasing effector CD8+ T-cell populations." (PMID 38283361, 2023). "In this review, we focused on analyzing the role of IL-21 in GB, but there are also other mediators that play an important role in the pathophysiology of this tumor, such as IL-1β." (PMID 37759505, 2023). "Another study utilized NFAT-inducible secreted IL-21, which demonstrated increased anti-tumor efficacy in NSG mice and resistance to immune suppression induced by chronic lymphocytic leukemia cells." (PMID 38090585, 2023). "Abnormal activation of Tfh cells and B cells mediated by CXCL13 and IL21 has been observed in tumor tissues." (PMID 37638029, 2023). "Tumor local delivery of IL-21 can skew TAM polarization away from the M2 phenotype to a tumor-inhibiting M1 phenotype, which rapidly stimulates T cell responses against tumors." (PMID 37628738, 2023). "Administration of IL21 by an intraperitoneal or intravenous route can reach both secondary lymphoid organs as well as the tumor." (PMID 37546701, 2023). "The IL-21 fusion protein inhibited tumor growth and demonstrated significant synergy with PD-1 blockade in advanced tumors." (PMID 37189417, 2023). "In vivo and in vitro studies have demonstrated IL-21 exerts diverse regulatory effects on healthy and tumor cells depending on the type of cell, stage of differentiation, stimuli, and EBV status." (PMID 36765813, 2023). "Increased numbers of IL21+ and IL26+ T cells have also been seen in PDAC and associate with an impaired clinical outcome, potentially through direct engagement with IL21R on tumor cells." (PMID 36689623, 2023). "First, the immune suppressive cytokines within the tumor microenvironments, including IL-10 and IL-21, were predominant." (PMID 37884996, 2023). "In a recent study, IL-21 fused with anti-EGFR or anti-CD20 exerted a more effective anti-tumor effect." (PMID 36936961, 2023). "Antibody-cytokine fusion proteins, such as anti-CD20/IFN-α, SumIL2/anti-EGFR, an-ti-PD1/IL-21, anti-EGFR/IL-21, arose to target these molecules in the tumor environment and demonstrated an improvement in either increased antitumor efficacy or reduced toxicity." (PMID 37047449, 2023). "It would induce additional TH9-driven mechanisms such as enhancing CD8 T cell function in an IL-21-dependent manner and direct cytotoxicity against tumor cells." (PMID 37189417, 2023).
tumor (continued). "IL-21-expressing cells exhibited greater cytotoxicity to tumor cells and greater survival in mice than IL-15 or IL-2 treated CAR-T cells despite higher levels of IFN-γ and Bcl-2 expression." (PMID 37064017, 2023). "Overall, preclinical studies have begun focusing on the development of IL-21 as an adjuvant drug for tumor treatment." (PMID 36936961, 2023). "We also analyzed the scRNA-seq data to determine how IL21, in combination with PD-1 blockade together, affects tumor-infiltrating CD4+ T cells in the TME." (PMID 37546701, 2023). "Interleukins, such as IL-2, IL-10, IL-12, IL15, and IL-21, and their receptors have been shown to be efficient mediators of anti-tumor immunity in preclinical cancer models." (PMID 37240247, 2023). "We and others have shown that IL21 administration can be combined with PD-1 blockade to synergistically inhibit tumor growth." (PMID 37546701, 2023). "Another engineering method is the incorporation of cytokine armoring genes, which leads to the production of cytokines required for T cell growth, including IL-15, IL-2, IL-7, IL-12, and IL-21, hence strengthening tumor-killing abilities." (PMID 37064017, 2023). "Initially, IL-21 was recognized for its anti-tumor effects in several preclinical tumor models, warranting its currently ongoing clinical development as a cancer immunotherapeutic." (PMID 38001643, 2023). "The researchers also indicate the effect of IL-21 expression on tumour growth by enhancing antibody-mediated neoplasm destruction and activating NK and CD3+CD8+ T cells." (PMID 36980527, 2023). "For example, anti-PD-1 antibody has been fused with IL-2, IL-15, or IL-21 to expand functional T cells and result in evident tumor remission." (PMID 38049832, 2023). "We then analyzed the scRNA-seq data to determine how IL21 in combination with PD-1 blockade together affect tumor-infiltrating regulatory T (Treg) cells." (PMID 37546701, 2023). "We further analyzed the scRNA-seq data to determine how IL21 in combination with PD-1 blockade together affect tumor-infiltrating CD8+ T cells." (PMID 37546701, 2023). "IL-21 has also been suggested to exhibit anti-tumor properties in lymphomas by expanding and enhancing tumor-infiltrating cytotoxic CD8+ T cells and NK cells." (PMID 36765813, 2023). "IL-21 is required for the generation of tumor-infiltrating CD8+ T cells expressing CX3CR1 characterized by cytolytic function and enhanced secretion of effector molecules such as interferon-γ and granzyme B." (PMID 36936961, 2023). "After a literature review, we collect factors that directly regulate the function of NK cells, and the gene list is IL2, IL15, IL18, IL21, all of which promote NK cell-mediated tumor death, while IL6, TGFβ and TNFα promote NK cell exhaustion." (PMID 38159250, 2023). "To summarize, IL-21, the most recently discovered of the IL-2 family cytokines, has great anti-tumor potential and has attracted considerable attention from the biomedical community." (PMID 36936961, 2023). "IL-21 was essential for tumor control and the transformation of the B-cells to anti-tumor IgG1 and IgG3 subtypes." (PMID 37671151, 2023). "Because it has been shown that the hyperactivated/exhausted CD8+ T-cell subset is enriched with tumor antigen–specific T cells, our data suggest that IL21 and anti-PD-1 in combination enhance the clonal expansion of the tumor antigen–specific CD8+ T cells." (PMID 37546701, 2023). "In recent years, some cytokines, including IL2, IL12, IL15, IL21, GM-CSF, and interferon-α, have been found to regulate the composition of tumor microenvironment and modulate the efficacy of immune therapy in murine cancer models." (PMID 36959575, 2023). "In various pre-clinical studies, K562 mb-IL21 expanded NK cells have shown to be highly efficient at preventing tumor establishment in human ovarian, lung, and breast cancer models." (PMID 38022679, 2023).